SLC7A11 (solute carrier family 7 member 11)
Diseases named in the same sentence as SLC7A11 in open-access papers (continued):
Sharing a sentence is not in itself a finding about the gene and the disease.
renal fibrosis (9 papers, 2022 to 2025). A final common manifestation of a wide variety of chronic kidney diseases characterized by glomerulosclerosis and tubulointerstitial fibrosis. "Several studies have concentrated on targeting ferroptosis and several potential underlying mechanisms through which SLC7A11 mitigates renal fibrosis have been proposed." (PMID 40249927, 2025). "Certain traditional Chinese medicine treatments can upregulate SLC7A11 expression and inhibit ferroptosis, leading to reduced renal fibrosis." (PMID 40249927, 2025). "Further studies are warranted to explore the role of SLC7A11 in mitochondrial dynamic imbalance and to investigate the contributions of mitophagy and ferroptosis to the progression of renal fibrosis." (PMID 40249927, 2025). "Various renal fibrosis models have consistently demonstrated SLC7A11 downregulation in renal fibrosis." (PMID 40249927, 2025). "In different kidney injury models, inhibiting the expression of Slc7a11 promotes ferroptosis, exacerbates lipid peroxidation, and accelerates renal fibrosis." (PMID 39931687, 2025). "Research has demonstrated that EZH2 can epigenetically regulate and downregulate SLC7A11 expression, leading to renal fibrosis." (PMID 40249927, 2025). "Specifically, it ameliorates renal fibrosis in DN by suppressing Smad3/NOX4/SLC7A11-mediated ferroptosis in tubular cells." (PMID 39769044, 2024). "Formononetin can suppress the Smad3/activating transcription factor 3/SLC7A11 signaling pathway, thereby ameliorating renal fibrosis induced by UUO and FA." (PMID 39769044, 2024). "SLC7A11 upregulation is accompanied by ferroptosis inhibition and an improvement in renal fibrosis." (PMID 40249927, 2025). "Correspondingly, SLC7A11 is upregulated by drugs that ameliorate renal fibrosis." (PMID 40249927, 2025). "Further research may provide a clearer understanding of the relationship between SLC7A11 and renal fibrosis and potentially lead to the development of targeted therapies." (PMID 40249927, 2025). "Therefore, SLC7A11 may affect renal fibrosis through both its effects on mitochondrial dynamics and ferroptosis." (PMID 40249927, 2025). "Recent research suggests that SLC7A11 plays a protective role in renal fibrosis, particularly through the SLC7A11/GPX4/GSH axis, which may inhibit ferroptosis in renal tubular epithelial cells and podocytes, thereby preventing kidney damage and reducing fibrosis." (PMID 40249927, 2025). "Additionally, SLC7A11 may affect renal fibrosis through other mechanisms, such as mitophagy." (PMID 40249927, 2025). "Ferroptosis is a significant contributor to renal fibrosis, with GPX4 and SLC7A11 serving as key markers, detected via Western blot." (PMID 40298655, 2025). "Formononetin inhibits the Smad3-ATF3-SLC7A11 pathway, increases SLC7A11 and GPX4 expression, promotes NRF2 nuclear accumulation, and ameliorates renal fibrosis and ferroptosis." (PMID 39857243, 2024). "In 2022, a study found that NAC combined with insulin administration upregulated the level of SLC7A11 mRNA in the kidney and increased the intracellular GSH concentration by nearly 4 times, thereby reducing renal fibrosis and improving renal function." (PMID 39872050, 2024). "However, the role of SLC7A11 in myofibroblasts, which are a crucial source of ECM during renal fibrosis, remains unclear." (PMID 40249927, 2025). "Despite the lack of consensus regarding the role of EMT in renal fibrosis, further research is warranted to assess whether SLC7A11 can improve fibrosis by improving EMT." (PMID 40249927, 2025). "After the intervention of SAL, renal fibrosis and ferroptosis in 8-month-old SAMP8 mice can be alleviated, which may be related to regulating renal iron metabolism, reducing iron deposition, regulating SLC7A11 and GPX4 protein expression, and finally alleviating renal ferroptosis." (PMID 36432138, 2022).
rheumatoid arthritis (9 papers, 2018 to 2025). A chronic, systemic autoimmune disorder characterized by inflammation in the synovial membranes and articular surfaces. "We evaluated the feasibility of SAS, an FDA-approved SLC7A11 inhibitor used for treating inflammatory diseases, including rheumatoid arthritis and ulcerative colitis." (PMID 37460542, 2023).
Alzheimer disease (8 papers, 2021 to 2025). A progressive, neurodegenerative disease characterized by loss of function and death of nerve cells in several areas of the brain leading to loss of cognitive function such as memory and language. "Prior research confirmed that the occurrence of ferroptosis in the Alzheimer’s disease mouse model was accompanied by a significant decrease in SLC7A11, SLC3A2, and FTH1 and an increase in the protein expression of DMT1 and NCOA4." (PMID 39635435, 2024). "In transgenic mice and in vitro models of Alzheimer’s disease, the gene expression of the two system xc− subunits SLC7A11 and SLC3A2 was found to be increased in the presence of β-amyloid." (PMID 34575878, 2021). "Biological validation and endophenotypic studies identified SLC7A11 as a top target relevant to liver and brain, and other genes related to often observed clinical comorbidities of chronic heavy AC, including hypertension and Alzheimer’s disease." (PMID 34857913, 2022). "In addition, the upstream mRNA expression of SLC7A11 and SLC3A2 was related to β-amyloid expression in transgenic mice and an in vitro model of human Alzheimer’s disease." (PMID 34575878, 2021). "The level of SLC7A11 notably declined in VD-deficient mice compared with the normal group, indicating that VD deficiency may downregulate the expressions of XcT through targeting VDR in Alzheimer’s disease." (PMID 38004239, 2023).
cardiac hypertrophy (8 papers, 2023 to 2025). "Moreover, Slc7a11 gene-encoded plasma membrane cystine/glutamate antiporter xCT exerts protective effects in Ang II-medicated cardiac hypertrophy by blocking ferroptosis." (PMID 37942067, 2023). "This interaction contributed to cardiac hypertrophy by binding to SLC7A11 mRNA, promoting its degradation, and consequently accelerating ferroptosis through the inhibition of GSH synthesis." (PMID 40000392, 2025). "This study elucidates the role of Zfp36 in cardiac hypertrophy, specifically detailing its modulatory mechanism via the Ythdc2/SLC7A11/GSH ferroptosis pathway." (PMID 40000392, 2025). "Collectively, these findings highlight the role of Zfp36 in modulating cardiac hypertrophy via the Ythdc2/SLC7A11/GSH‐dependent ferroptosis pathway." (PMID 40000392, 2025). "This study provides compelling evidence, for the first time, that Zfp36 is integral in suppressing ferroptosis and reducing cardiac hypertrophy through the Ythdc2/SLC7A11/GSH axis in cardiomyocytes (Graphical Abstract)." (PMID 40000392, 2025). "Ythdc2 can bind to SLC7A11 mRNA to accelerate its decay, thereby reducing glutathione levels and aggravating ferroptosis‐induced cardiac hypertrophy." (PMID 40000392, 2025). "This study examines the regulatory influence of Ythdc2 on SLC7A11 within the context of cardiac hypertrophy." (PMID 40000392, 2025). "This regulatory mechanism is pertinent in the context of cardiovascular diseases, as demonstrated by SLC7A11's role in preventing Ang II‐induced cardiac hypertrophy through ferroptosis inhibition." (PMID 40000392, 2025). "Ythdc2 subsequently binds to SLC7A11 mRNA, enhancing its decay, which leads to a reduction in glutathione (GSH) levels, thereby exacerbating ferroptosis and cardiac hypertrophy." (PMID 40000392, 2025). "Ythdc2 interacts with SLC7A11 mRNA, facilitating its degradation and resulting in decreased GSH levels, thereby modulating ferroptosis in cardiomyocytes and influencing cardiac hypertrophy." (PMID 40000392, 2025).
COVID-19 (8 papers, 2021 to 2025). A disease caused by infection with severe acute respiratory syndrome coronavirus 2. "A weighted gene co‐expression network analysis (WGCNA) of RNA-sequencing dataset revealed four key genes, PROK2, IL6, TNF, SLC7A11, closely related to COVID-19 ALI41." (PMID 38769293, 2024). "Because several independent studies have reported a higher risk of death for COVID-19 patients treated with Sulfasalazine, possibly associated with SLC7A11-independent inhibition of type I interferon production in vivo, we selected IKE to inhibit SLC7A11 in the following study." (PMID 38305139, 2024). "We found that in the BD–COVID-19 interaction, genes RRM2, IFNAR2, and SLC7A11 and miRNAs hsa-mir-30a-5p, hsa-mir-93-5p, and hsa-mir-192-5p have more significant effects." (PMID 35185890, 2022). "In addition, serum from coronavirus disease 2019 (COVID-19) non-survivors triggers ferroptosis in endothelial cells, which was manifested by elevated lipid peroxidation levels and decreased expression of GPX4, SLC7A11, and ferritin heavy chain (FTH1)." (PMID 39251905, 2024).
depression (8 papers, 2019 to 2025). "One of the key findings of this study is that both mRNA and protein levels of GPX4, SLC3A2, and SLC7A11 were significantly downregulated in the PFC of ELS mice, and that some of these genes were specifically associated with depression-like behaviors." (PMID 41154206, 2025). "Crucially, knockdown of hippocampal SLC7A11 abrogated the protective effects of nicorandil on depression‐like behaviors, lipid peroxidation, and ferroptosis in the hippocampus of rats with TBI." (PMID 39739538, 2025). "The ferroptosis-related IRF1/SLC7A11/GPX4 signaling pathway also plays an important role in depression." (PMID 40177374, 2025). "Taken together, our results reveal that nicorandil attenuates depression following TBI via facilitating the SLC7A11/GPX4 axis to suppress hippocampal ferroptosis." (PMID 39739538, 2025). "This suggests that targeting the SLC7A11/GPX4 axis to regulate ferroptosis may offer new therapeutic strategies for TBI‐related depression." (PMID 39739538, 2025). "Given the significant role of ferroptosis in exacerbating post‐TBI complications, our study focuses on exploring whether nicorandil mitigates depression‐like behaviors in a rat model of TBI by activating the SLC7A11/GPX4 axis, thus reducing hippocampal ferroptosis." (PMID 39739538, 2025). "Mechanistically, nicorandil suppresses ferroptosis via promoting the SLC7A11/GPX4 axis in the hippocampus of rats with TBI, thus ameliorating depression‐like symptoms induced by TBI." (PMID 39739538, 2025). "The expression levels of GPX4, SLC3A2, SLC7A11, TFR1, and lipid peroxidation markers in the PFC of mice were measured and correlated with depression-like behavioral changes." (PMID 41154206, 2025). "In the LPS-induced depression model, the demethylation function of m6A-modified PRMT2 mRNA is inhibited, resulting in increased expression of PRMT2 in BV2 cells and the hippocampus, while ALKBH5, SLC7A11, and GPX4 expressions decrease, facilitating ferroptosis." (PMID 40177374, 2025). "Moreover, SLC7A11 knockdown blocks the nicorandil‐induced reduction in ferroptosis, further supporting the hypothesis that the therapeutic benefits of nicorandil in TBI‐related depression are mediated through its anti‐ferroptotic actions." (PMID 39739538, 2025).
lung squamous cell carcinoma (8 papers, 2021 to 2026). "We also found that SLC7A11 was overexpressed both in LUAD and lung squamous cell carcinoma (LUSC)." (PMID 34722530, 2021).
myocardial ischemia (8 papers, 2022 to 2025). A disorder of cardiac function caused by insufficient blood flow to the muscle tissue of the heart. "There is evidence that SLC7A11 plays a protective role in myocardial ischemia/reperfusion, and the mechanism is that overexpressed SCL7A11 inhibits ferroptosis in cardiomyocytes." (PMID 39666769, 2024). "In a myocardial ischemia–reperfusion injury model, isoliquiritigenin reduces oxidative stress and ferroptosis by promoting Nrf2 nuclear translocation and activating the expression of HO-1, SLC7A11, and GPX4." (PMID 40298739, 2025). "Research has confirmed that hydroxysafflor yellow A (HSYA) can inhibit myocardial cell ferroptosis by activating HIF-1α, which ultimately increases the expression of SLC7A11 and GPX4, thereby reducing myocardial ischemia/reperfusion injury in mice." (PMID 40691131, 2025).
tongue squamous cell carcinoma (8 papers, 2017 to 2025). A squamous cell carcinoma that arises from the tongue. "Our study revealed that the genes SLC3A2 and SLC7A11, which are associated with disulphide death, are enriched in tongue squamous cell carcinoma (TSCC)." (PMID 37927242, 2023). "Another study showed that miR-125b-5p could directly bind to the 3′ UTR of SLC7A11 and inhibit the expression of SLC7A11 in tongue squamous cell carcinoma (TSCC)." (PMID 35328568, 2022). "In tongue squamous cell carcinoma, EZH2 repression of miR-125b-5p has been reported, leading to enhanced SLC7A11 expression, thereby averting erastin-induced ferroptosis." (PMID 39516467, 2024). "SLC7A11, mediated by EZH2, regulated the ferroptosis in tongue squamous cell carcinoma." (PMID 35997855, 2023). "In tongue squamous cell carcinoma, EZH2 inhibits erastin-induced ferroptosis through the miR-125b-5p/SLC7A11 pathway rather than the H3K27me3 pathway." (PMID 41372608, 2025).
acute liver failure (7 papers, 2021 to 2025). Rapid deterioration of liver function causing encephalopathy and coagulopathy. "HBV X protein (HBx) facilitates ferroptosis in acute liver failure by EZH2-mediated SLC7A11 suppression." (PMID 39518098, 2024). "Similar to the results of our experiments, EZH2 was reported to promote ferroptosis by suppressing SLC7A11 expression in a D-galactosamine-induced acute liver failure model." (PMID 38169402, 2024). "For instance, EZH2-mediated SLC7A11 modulated ferroptosis in acute liver failure." (PMID 35997855, 2023).
amyotrophic lateral sclerosis (7 papers, 2020 to 2024). Amyotrophic lateral sclerosis (ALS) is a neurodegenerative disease characterized by progressive muscular paralysis reflecting degeneration of motor neurons in the primary motor cortex, corticospinal tracts, brainstem and spinal cord. "Whereas SLC7A11 is not expressed in motor neurons, SLC7A11 expression is induced in activated microglia in amyotrophic lateral sclerosis (ALS) mice carrying mutant SOD1, the gene encoding cytosolic superoxide dismutase (SOD)." (PMID 37175751, 2023).
Cognitive impairment (7 papers, 2020 to 2025). Abnormal cognition is characterized by deficits in thinking, reasoning, or remembering. "The activation of some signaling molecules will eventually play a vital part through SLC7A11, as demonstrated in the study on protective strategies against oxidative stress and ferroptosis in patients with cognitive impairment after IS." (PMID 38393376, 2024). "Furthermore, another study showed that Rehmannioside A reduced oxidative stress, diminished infarct volume, and improved cognitive impairment in I/R rats by attenuating ferroptosis through the PI3K/Nrf2/SLC7A11 pathway." (PMID 39042604, 2024). "Research has shown that the deletion of SLC7A11 or GPX4 in mice could cause ferroptosis-like damage, lead to cognitive impairment and neurodegeneration, and even show early embryonic lethality." (PMID 36909944, 2023). "Rehmannioside A ameliorated cognitive impairment and alleviated ferroptosis by activating the PI3K/Nrf2/SLC7A11 signaling pathway." (PMID 38393376, 2024).
nasopharyngeal carcinoma (7 papers, 2024 to 2025). A carcinoma arising from the nasopharyngeal epithelium. "In personalized treatment, integrating METTL3 and SLC7A11 expression levels for patient stratification may offer more precise treatment plans for nasopharyngeal carcinoma patients." (PMID 39990661, 2025). "In nasopharyngeal carcinoma, Epstein-Barr virus infection triggers the p62-KEAP1-NRF2 axis, upregulating SLC7A11 and GPX4, which decreases sensitivity to ferroptosis." (PMID 39935430, 2025). "Similarly, circADARB1 promotes radiotherapy resistance in nasopharyngeal carcinoma (NPC) by stabilizing SLC7A11/GPX4 through HSP90B1 upregulation." (PMID 40403492, 2025).
Obesity (7 papers, 2021 to 2025). Accumulation of substantial excess body fat. "Arbutin, a natural antioxidant, inhibits obesity-associated protein (FTO), which increases the m6A methylation level of SLC7A11, promotes the expression of SLC7A11, and ultimately inhibits iron death, slowing down the progression of NAFLD in vivo and in vitro." (PMID 41050396, 2025). "Accordingly, AMPK activation based on the low expression of SLC7A11 altering the cellular sensitivity to ferroptosis under HFD treatment was mechanistically responsible for the distinctive antitumor activity of SGF in obesity-related CRC." (PMID 40141120, 2025). "In this example, 16 DMSs in genes, such as CPT1A, ABCG1, SLC7A11, RNF145, and SREBF1 were reported to be associated with obesity-related phenotypes." (PMID 35047011, 2021).
osteoporosis (7 papers, 2021 to 2026). A condition of reduced bone mass, with decreased cortical thickness and a decrease in the number and size of the trabeculae of cancellous bone (but normal chemical composition), resulting in increased fracture incidence. "circSlc7a11 is formed by pre-mRNA back splicing of the Slc7a11, which encodes a cystine–glutamate transporter protein with various biological and pathogenic functions, including epileptic seizures and osteoporosis." (PMID 33433832, 2021). "Through high‐throughput virtual screening, this work identifies Pantethine as a potent PSMD14 activator that enhances deubiquitinase activity, restores SLC7A11 expression in osteocytes, and mitigates osteoporosis." (PMID 40444470, 2025). "Among absorbable components in AA, mangiferin has acted as a ferroptosis inhibitor through the Keap1/Nrf2/SLC7A11/GPX4 pathway in osteoporosis mice." (PMID 39512823, 2024). "And the key proteins discovered from animal models, such as GPX4, SLC7A11, ACSL4, etc., are extremely difficult and unethical to obtain from healthy human bodies, especially in early bone tissue samples of osteoporosis." (PMID 41551515, 2025). "Our previous work revealed that activation of the SLC7A11/GPX4 signaling pathway inhibits the onset of ferroptosis, and eventually attenuates osteoporosis." (PMID 39512823, 2024). "Alterations in the expression of ferroptosis biomarkers, such as GPX4, SLC7A11, and SLC3A2, have been observed in the steroid-induced osteoporosis context." (PMID 36854703, 2023).